ATM (ATM serine/threonine kinase)
Diseases named in the same sentence as ATM in open-access papers (continued):
Sharing a sentence is not in itself a finding about the gene and the disease.
glioma (continued). "Here, we demonstrate that the effect of these drugs on the proliferation and survival of human glioma cells can be greatly potentiated by combining PDGFR inhibitor treatment with ATM inhibitors." (PMID 26984279, 2016). "Since the DNA damage checkpoints are essential for cellular radiosensitivity, we determined the activation of the ataxia-telangiectasia-mutated protein (ATM) after incubation with [I-125]ITdU in CD133+ and CD133− glioma cells." (PMID 24978848, 2014). "Following radiation, CD133+ glioma stem cells exhibited much higher activated phosphorylation of DNA damage response factors ATM, CHK1 and CHK2 than CD133- glioma cells." (PMID 23369605, 2013). "Here we investigate the role of 10 potential SNPs in XRCC3, BRCA2, RAG1, XRCC5, LIG4, XRCC4 and ATM in the development of gliomas, and further evaluate their gene-gene and gene-environment interactions in the development of glioma." (PMID 23663450, 2013). "Pathogenic GVs in ATM were found in each family type with the highest fraction in glioma families, but not in multiple tumor glioma patients." (PMID 41546701, 2026). "Blood–brain barrier penetrant PARP inhibitors may be effective in glioma patients carrying GVs in ATM, BRCA2, BRIP1, FANCA, and SDHA identified here that are associated with HRR deficiency, and may act synergistically with radio-, chemo-, and immunotherapy." (PMID 41546701, 2026). "Five of six ATM GV carriers were diagnosed with a glioma before 50 years of age." (PMID 41546701, 2026). "The mean nuclear IRS of phospho-H2AX indicating DSB accumulation was lowest in gliomas from SDHA versus ATM, BRCA2, and FANCA GV carriers, although the differences were not statistically significant, possibly because SDHA variants are least directly linked to impaired DSB repair." (PMID 41546701, 2026). "Finally, besides employing small molecule ATMi, silencing of ATM or ATR using siRNA has also been shown to increase glioma cell chemo- and radiosensitivity." (PMID 35406593, 2022). "Moreover, nuclear levels of γ-H2AX, phospho-ATM and phospho-DNAPKcs were all up-regulated in shikonin-treated gliomas." (PMID 36038617, 2022). "Thus, inhibition of ATM sensitized TMZ-sensitive but notresistant glioma cell lines to treatment with TMZ." (PMID 35158967, 2022). "Treatment with ATM- or ATR-inhibitors (ATMi/ATRi) may thus selectively sensitize glioma cells and GSCs to IR and/or TMZ." (PMID 35406593, 2022). "Post-transcriptional ATM regulation mediated by microRNAs has been reported in gliomas and BC." (PMID 34068084, 2021). "In addition, the treatment with ATM inhibitors increased the radiosensitivity of glioma cells and glioblastoma stem cells in vitro." (PMID 33224881, 2020). "Upregulation of wild-type (wt) EGFR or expression of the EGFR variant III (EGFRvIII) have been associated in U87 glioma cells with promotion of γ-H2AX foci resolution, a surrogate for DSB repair, and with the nuclear accumulation of ATM, DNA-PKcs and RAD51, essential for the activity of NHEJ and HR." (PMID 28587121, 2017). "In addition, ATM expression was determined by qPCR in RNA isolated from FFPE biopsy specimens from primary low-grade glioma (WHO classification I and II), GBM (WHO classification IV), and histologically benign brain samples." (PMID 29348882, 2017). "Indeed, it has been shown that the PI3K/AKT inhibitor BEZ-235 inhibits DNA damage response proteins, including ATM and DNA-PKcs, in glioma, and the PI3K inhibitor LY294002 enhances the efficacy of radiotherapy in cervical cancer." (PMID 29348875, 2017).
glioma (continued). "Moreover, self-inflicted DNA DSB formation and ATM activation are important in sustaining the stemness of patient-derived glioma cells." (PMID 28337983, 2017). "Interestingly, compared with vector control-transduced cells, glioma cells with ATM knockout showed significantly less CD133 expression and reduced levels of activated STAT3." (PMID 28337983, 2017). "We genotyped 10 potentially functional single nucleotide polymorphisms (SNPs) in 7 DNA double-strand break repair pathway genes (XRCC3, BRCA2, RAG1, XRCC5, LIG4, XRCC4 and ATM) in a case–control study including 384 glioma patients and 384 cancer-free controls in a Chinese Han population." (PMID 23663450, 2013). "ATM gene is a novel target for epigenetic silencing through inappropriate methylation of its proximal promoter region correlates with increased radiosensitivity and low protein expression in a human colorectal tumor cell line and human glioma cell line." (PMID 24324828, 2013). "The significantly younger age at glioma diagnosis of ATM GV carriers may at least partly be explained by the younger median age of patients presenting with IDH-mutant astrocytoma (38 years), compared with a peak incidence of IDH-wildtype glioblastoma between 55 and 85 years." (PMID 41546701, 2026). "Beyond personalized radiation dose planning, we could cautiously assume that whole brain or large field RT rather than focal RT might be an effective personalized treatment option with excellent in-field control and prolonged survival in patients with IDH-wildtype ATM mut(+) high-grade glioma." (PMID 32736562, 2020). "Similarly, CH variants in ATM have been observed in ALL, astrocytoma, and high-grade glioma." (PMID 32508881, 2020). "We demonstrated that ATM mutations in IDH-wildtype high-grade glioma could yield an excellent RT response, irrespective of the adverse features of gliomatosis or the involvement of the SVZ." (PMID 32736562, 2020). "To identify the association between somatic ataxia-telangiectasia mutated (ATM) mutations and improved radio-sensitivity, we retrospectively reviewed next-generation sequencing data from patients diagnosed with isocitrate dehydrogenase (IDH)-wildtype high-grade glioma." (PMID 32736562, 2020). "In the experiments reported here with two well-characterized glioma lines we demonstrate that a) autophagy precedes apoptosis, b) inhibition of autophagy by 3-MA ameliorates the level of apoptosis, and c) downregulation of ATM inhibits autophagy and ameliorates apoptosis." (PMID 23383259, 2013). "For solid tumors, crizotinib + dasatinib in low-grade glioma (87% responders; active in 16 cancer types) and AZD0156 (ATM/ATRi) plus olaparib (PARPi) in Ewing's sarcoma (84% responders; active in 16 cancer types) were high scoring." (PMID 38456804, 2024). "Unlike the results mentioned, we found that inhibition of ROCK2 decreased the ATM level in U87R and U251R cells, induced DSB and impaired DNA repair, suggesting that a novel mechanism was responsible for DSB repair in TMZ-R gliomas." (PMID 35145081, 2022). "DNA double-strand breaks (DSBs) and blocked DNA replication forks activate the DDR kinases ATM, ATR, CHK1 and CHK2 and these kinases protect glioma cells against TMZ-induced cell death." (PMID 35365623, 2022).
glioma (continued). "Glioma cells co-treated with TMZ and ATM, ATR, or MRN inhibitors significantly decrease the number of SA-β-gal positive cells, suggesting this DDR axis also plays a role in senescence." (PMID 35626024, 2022). "Glioma cells, especially GSCs, exhibit increased resistance to IR, which is mediated by an upregulation of DDR targets such as ATM, ATR, PARP1, and CHK1." (PMID 35406593, 2022). "These O6MeG-dependent replication blocking lesions activate the DNA damage response (DDR) kinases ATM and ATR, thereby initiating bypass in glioma cells in a tolerance mechanism that requires homologous recombination (HR)." (PMID 35365623, 2022). "IPA analysis of the integrated data indicated that volasertib modulates glioma relevant pathways including glucocorticoid receptor, AMPK, ATM and ERK/MAPK." (PMID 34680264, 2021). "The ATM inhibitor (ATMi; KU-60019) and ATR inhibitor (ATRi; AZD6738) potently inhibit their target and effectively sensitised glioma cells (ATMi) and NSCLC cells (ATRi) to radiation and were used at doses with confirmed target inhibition." (PMID 33824328, 2021). "In this context, we undertook a retrospective analysis of NGS data to address the radio-sensitivity of ATM mut(+) and its impact on clinical outcomes in patients with IDH-wildtype high-grade glioma." (PMID 32736562, 2020). "A potent ATM-specific inhibitor KU-60019 can attenuate AKT phosphorylation at Ser473 and interfere with cell growth in human glioma cells and enhance apoptotic cell death and alleviate senescence." (PMID 32665601, 2020). "To establish the functional relevance of STAT3 as a downstream effector of ATM in maintaining the stemness of glioma stem cells, we transduced D456MG-ATM KO cells with a constitutively active STAT3 (STAT3C) or a dominant-negative STAT3 (STAT3DN)." (PMID 28337983, 2017). "The effect of ATM-KO on cell proliferation was monitored daily by cell counting, and ATM-KO was found to inhibit the proliferation of both MT330 and SJG2 glioma cells." (PMID 29348882, 2017). "The use of the specific ATM inhibitor KU-60019 has been proven to reduce DDR, glioma cell migration and invasion by downregulating basal activation of Akt." (PMID 28587121, 2017). "ATM expression was highest in GBM, and markedly lower in both benign brain tissue and low-grade glioma." (PMID 29348882, 2017). "In order to show a causal relationship between spDSB-induced ATM activation and stemness of the glioma cells, we used a multiplex CRISPR-sgRNA vector to target the ATM gene." (PMID 28337983, 2017). "Our results indicate that glioma cells with caspase-3 or ATM knockout had significantly reduced abilities to form tumor spheres than control in both T4121 and D456MG glioma cells." (PMID 28337983, 2017). "The ATM inhibitor ku-55933 can abrogate the ATM-AMPK signaling pathway, which further enhances TMZ cytotoxity in glioma cells." (PMID 26830677, 2016). "Meanwhile, the interruption of the ATM-AMPK pathways ku-55933 inhibits the cytoprotective process of autophagy, which results in the augmentation of the TMZ cytotoxic effect and promotes glioma cell death under apoptotic stress." (PMID 26830677, 2016).
glioma (continued). "We investigated levels of multiple drug resistance-related genes in U87 and primary glioma cells, including genes related to drug efflux (ABCB1, ABCC1, ABCC2, ABCC4, ABCG2, ATM), DNA damage repair (MGMT) and stemness (CD133)." (PMID 27486877, 2016). "A semi-quantitative analysis of ATM and BRCA2 staining revealed a trend towards a lower mean nuclear IRS for ATM in gliomas from ATM GV versus non-ATM GV carriers, and for BRCA2 in gliomas from BRCA2 GV versus non-BRCA2 GV carriers." (PMID 41546701, 2026). "ATM GV carriers had a significantly younger median age at glioma diagnosis compared to non-GV carriers (36 versus 58 years, P = 0.022)." (PMID 41546701, 2026). "In this study, heterozygous GVs in ATM predisposed mainly to IDH-mutant astrocytoma at a median age of 36 years, compared to 58 years at primary glioma diagnosis in patients without GVs, mainly affected by glioblastoma." (PMID 41546701, 2026). "The CPGs most frequently affected by GVs were ATM in 6/206 (2.9%) families, BRCA2 in 5/206 (2.4%) families (identified in approaches 1 and 2), GBA1 in 4/206 (1.9%) families as well as EGFR, GJB2, and SDHA in 3/206 (1.5%) families each of the glioma cohort." (PMID 41546701, 2026). "Astrocytoma, IDH-mutant was diagnosed significantly more frequently in glioma patients with ATM GVs than in those without GVs (4/6 versus 20/140, P = 0.007)." (PMID 41546701, 2026). "The potential role of cell cycle checkpoint inhibition in the treatment of high-grade glioma was supported by the dose-dependent radiosensitizing effect of MEK162, the MAPK-targeting agent, which downregulated the expression of WEE1, ATM, and CHK2 kinase, as well as CDK1 and CDK2." (PMID 35158967, 2022). "Particularly, artesunate, an artemisinin's derivative, provoked a DDR with phosphorylation of ATM, ATR, CHK1, and CHK2 in LN-229 glioma cells after 8-hour treatment, while timosaponin AIII activated DDR through the ATM-CHK2 pathway in MCF-7 cells after treatment for 10–20 min." (PMID 35287310, 2022). "ATM and ATR were reported play vital roles in treatment-resistance in gliomas." (PMID 34483751, 2021). "Therefore, it appeared mechanistically ATM promotes stemness in glioma cells by phosphorylating and activating STAT3, which has been to be a crucial factor in glioma stem cells." (PMID 32566127, 2020). "Next-generation sequencing (NGS) of three cases identified mutations in a few genes known to be altered in low-grade gliomas, (e.g., BCOR, BCORL1, ERBB3, MYB, and ATM), but no recurrent mutations were seen." (PMID 31114608, 2019). "The two low-grade glioma tissues analyzed were almost negative for the markers, with the exception of p-ATM and γ-H2AX, poorly positive at level of mitoses." (PMID 25892134, 2015).
glioma (continued). "An effect of ATM variants on the radio-sensitivity of gliomas was previously reported, with significantly higher 1-year in-field control rates after radiation therapy in IDH-wildtype high-grade gliomas with versus without somatic pathogenic ATM variants." (PMID 41546701, 2026). "Moreover, the levels of p-ATM, p-H2AX, PARP1 and PAR were all increased in DPT-treated gliomas." (PMID 37186123, 2023). "In a study on glioma-initiating cells comparing the effect of KU55933 with an abrogation of NHEJ by a DNA-dependent protein kinase inhibitor (DNA-PKi), the combination of ATM inhibition and RT prolonged the survival of tumor-bearing mice, suggesting that HR dominates the survival of these cells." (PMID 35158967, 2022). "Thus, targeting ATM is considered to be an appropriate strategy for synthetic cancer cell-killing therapies, and specific ATM inhibitors such as KU60019 have been reported to be improved glioma treatment." (PMID 35795059, 2022). "On the other hand, genetic knockout of ATM in human glioma cells showed significantly less expression of CD133, Oct4, Nestin, and activated STAT3, four important markers of glioma CSCs, suggesting that ATM activation were directly responsible for glioma CSC maintenance." (PMID 32566127, 2020). "We report a 19-year-old female with a non-enhancing, diffuse pediatric-type high-grade glioma, H3-wildtype and IDH-wildtype, harboring a germline ATM alteration." (PMID 41878701, 2026). "In this study, we found that the mutant genes in the metastatic brain tumors included ALK, MDM2, ATM, BRCA1, FGFR1, and KRAS, and there were no glioma-related mutant genes (MGMT, IDH1, IDH2, 1p/19q, BRAF, and TERT)." (PMID 32973641, 2020). "Apart from its impacts on ATM and HIPK2, ClQ also affects the abundance of anti-apoptotic kinase AKT in company with inhibiting autophagy, a condition that induces death in non-stem glioma cells." (PMID 37174691, 2023).